SYN1 (synapsin I)
Description:
Neuronal phosphoprotein that coats synaptic vesicles, and binds to the cytoskeleton. Acts as a regulator of synaptic vesicles trafficking, involved in the control of neurotransmitter release at the pre-synaptic terminal. Also involved in the regulation of axon outgrowth and synaptogenesis (By similarity). The complex formed with NOS1 and CAPON proteins is necessary for specific nitric-oxid functions at a presynaptic level (By similarity).
Synonyms: EPILX; EPILX1; MRX50; SYN1a; SYN1b; SYNI
Tractability: PROTAC: its protein half-life has been measured.
Gene: Protein-coding gene on chromosome X (47,571,901 to 47,619,858, reverse strand). Ensembl gene ENSG00000008056.
Subcellular location: Synapse; Golgi apparatus; Presynapse; Cytoplasmic vesicle, secretory vesicle, synaptic vesicle
Pathways (Reactome):
Neuronal System: Dopamine Neurotransmitter Release Cycle; Serotonin Neurotransmitter Release Cycle
Sensory Perception: Sensory processing of sound by inner hair cells of the cochlea
Gene Ontology:
Molecular function: protein binding; ATP binding; cytoskeletal protein-membrane anchor activity; protein kinase binding; identical protein binding
Biological process: regulation of synaptic vesicle exocytosis; chemical synaptic transmission; regulation of neurotransmitter secretion; synapse organization; synaptic vesicle clustering; modulation of chemical synaptic transmission; neurotransmitter secretion; regulation of synaptic vesicle cycle; synaptic vesicle cycle
Cellular component: cytoskeleton; presynapse; Golgi apparatus; synapse; synaptic vesicle; synaptic vesicle membrane; axon; cell body; dendrite; postsynaptic density; presynaptic active zone; Schaffer collateral - CA1 synapse; synaptonemal complex
Gene-disease validity (ClinGen):
ClinGen rates the evidence that SYN1 causes each of these diseases.
X-linked complex neurodevelopmental disorder (X-linked): Definitive. A complex neurodevelopmental disorder that is transmitted via X-linked inheritance, and is characterized by intellectual disability, autism and epilepsy.
Homologues: Orthologues: chimpanzee SYN1 (100% identical), macaque SYN1 (99% identical), pig SYN1 (98% identical), mouse Syn1 (96% identical), rat Syn1 (96% identical), guinea pig SYN1 (93% identical), dog SYN1 (91% identical), rabbit SYN1 (85% identical), tropical clawed frog syn1 (66% identical), Caenorhabditis elegans snn-1 (19% identical). Paralogues in human: SYN2 (52% identical), SYN3 (48% identical).
Diseases named in the same sentence as SYN1 in open-access papers:
SYN1 is named in the same sentence as 119 diseases in open-access papers, as found by Europe PMC text mining. Sharing a sentence is not in itself a finding about the gene and the disease. The quoted sentences say what the papers report.
epilepsy (35 papers, 2013 to 2026). A brain disorder characterized by episodes of abnormally increased neuronal discharge resulting in transient episodes of sensory or motor neurological dysfunction, or psychic dysfunction. "Particularly, SYN1-associated epilepsy is characterized by reflex seizures triggered by bathing or showering." (PMID 38612920, 2024). "Evidence that loss of function genetic mutations in SYN1 have been associated with ASD and epilepsy, and SYN1 knockout mice display impaired social behaviors and repetitive behaviors, supports this possibility." (PMID 38355786, 2024). "This is intriguing given that patients with LoF variants in SYN1 display a similar phenotype with epilepsy, ID, ASD, macrocephaly, and behavioral abnormalities." (PMID 36742338, 2023). "We note that case ascertainment in many studies describing the clinical features of individuals with SYN1 variants has been weighted towards individuals with epilepsy." (PMID 36568968, 2022). "In humans, variants in SYN1 have been independently associated with epilepsy, learning disabilities and behavioral disorders (OMIM #300491) or non-syndromic intellectual disability (OMIM #300115)." (PMID 36568968, 2022). "Correspondingly, alterations of synaptic homeostasis consequent to variants in SYN1 have been shown to lead to disease phenotypes mainly characterized by epilepsy, ID, DD, and ASD." (PMID 36568968, 2022). "Further studies identified additional nonsense and missense mutations in Syn1 associated with intellectual disabilities, autism, and epilepsy, thus supporting a role for synapsins in human epilepsies." (PMID 35326282, 2022). "Here, we found an association between toothbrushing epilepsy and SYN1 gene mutation, and added toothbrushing as another environmental trigger for SYN1-related RE." (PMID 34616357, 2021). "We identified a novel X-linked SYN1 exon 12 mutant gene in a Chinese family with toothbrushing epilepsy." (PMID 34616357, 2021). "Mutation of this particular gene (SYN1), albeit a different type of mutation, was identified in this study and was found to be correlated with toothbrushing epilepsy." (PMID 34616357, 2021). "All three affected men in the family in this study were hemizygous for the SYN1 c.1807C>T (p.Q603Ter) nonsense mutation, suggesting an association between the SYN1 mutant allele and toothbrushing epilepsy." (PMID 34616357, 2021). "Variants in SYN1 have been associated with learning difficulties, epilepsy, and aggressive behavior." (PMID 31906484, 2020). "Using knockout experiments in mice, it has been shown that Synapsins are involved in learning and memory, and SYN1 has been implicated in human neurological diseases, such as learning difficulties and epilepsy." (PMID 32641419, 2020). "Nonsense and missense mutations in SYN1/SYN2 genes have been identified as causative for epilepsy and autism spectrum disorder (ASD) in humans." (PMID 29721159, 2018). "Mutations in the phosphorylation domains of SYN1 essential for vesicle recycling control have been related to epilepsy." (PMID 30115750, 2018). "The SYN1 missense mutation A550T was isolated in four patients: two with epilepsy, one with autism, and one with both, whereas, the missense mutation T567A was isolated in two individuals with ASD only." (PMID 25237665, 2014). "Two SYN1 nonsense mutations, causing truncations at protein level (W356X and Q555X), were identified in two large families with epilepsy with recessive X-linked transmission." (PMID 25237665, 2014). "This is particularly compelling because SYN1 mutations associated with epilepsy and ASDs are concentrated in the D domain, a region that physically binds to vesicles; mutations in this region impair vesicle pool size and trafficking." (PMID 24312498, 2013). "Synapsin knock-out (Syn1−/−) mice display an epileptic phenotype and mutations in the SYN1 gene have been identified in individuals affected by epilepsy and/or autism spectrum disorder." (PMID 23818987, 2013).
epilepsy (continued). "Nonsense and missense mutations in SYN1 were recently described in association with epilepsy and/or autism spectrum disorders." (PMID 23818987, 2013). "Interestingly, one study found mutations in the SYN1 gene associated with autism spectrum disorders and epilepsy." (PMID 41596330, 2026). "While monoallelic loss of function (LoF) variants in the SYN1 gene result in X-linked intellectual disability (ID), learning disabilities, epilepsy, behavioral problems, and macrocephaly, the effect of SYN1 autoantibodies on neurodevelopment remains unclear." (PMID 36742338, 2023). "Patients with loss of function (LoF) variants in the SYN1 gene have been associated with X-linked phenotypes consisting of epilepsy, learning difficulties, intellectual disability (ID), macrocephaly, behavioral problems, and autism-spectrum disorders (ASD) (MIM#300491, MIM#300115)." (PMID 36742338, 2023). "The finding that epilepsy developed in 83% of SYN1 variant carriers published to date suggests that early molecular diagnosis of a SYN1 variant (for example, in children born within families known to carry a variant) should alert clinicians to the need for careful surveillance for possible seizures." (PMID 36568968, 2022). "Furthermore, our analyses suggested the potential of SYN1 nonsense mutation as a candidate biomarker for the diagnosis of toothbrushing epilepsy." (PMID 34616357, 2021). "Bathing epilepsy is genetically distinct reflex epilepsy caused mainly by SYN1 mutations." (PMID 34078716, 2021). "In all families with bathing epilepsy, we identified 8 distinct pathogenic or likely pathogenic variants and 2 variants of unknown significance in SYN1, 9 of which are novel." (PMID 34078716, 2021). "Besides its physiological role in synaptic plasticity regulation, SYN1 has been associated with epilepsy." (PMID 30115750, 2018). "SYN1/2 genes are major epilepsy susceptibility genes in humans." (PMID 29163811, 2017). "Mutations in SYN1 have been associated with epilepsy and autism spectrum disorder." (PMID 26909693, 2016). "While no mutations in the SV2 genes have been found to be associated with human epilepsy to date, a first nonsense (c.1067G>A) mutation in the SYN1 gene was described in 2004 in a four-generation family affected by a syndromic form of inherited X-linked epilepsy." (PMID 23818987, 2013). "There are numerous forms of SYN1-related epilepsy including X-linked epilepsy with variable learning disabilities and behavior disorders, bathing epilepsy, hot water epilepsy that may involve GTCS and/or focal unaware seizures, with no fixed age of seizure onset or termination." (PMID 34616357, 2021). "Genetic mutations in SYN1 resulting in loss of function have also been associated with ASD and epilepsy." (PMID 38355786, 2024). "BE is a clinically and genetically homogeneous distinct RE and should be considered a handle for the molecular diagnosis of SYN1-related epilepsy." (PMID 34078716, 2021). "Mutations in the SYN1 and SYN2 genes are associated with epilepsy and/or ASD and the identification of the pathogenic mechanisms leading to the overt clinical manifestations is fundamental to establish personalized therapies." (PMID 29163811, 2017). "The brown module has 53 hub genes, including genes associated with dopaminergic signaling (GNB1, GSK3B), long-term potentiation (PPP1CB), opioid signaling (PPP2CA, PPP3CA, PPP3R1), epilepsy (SYN1), and Parkinson’s disease (SNCA)." (PMID 28710498, 2017). "Further clues come from the obvious comorbidity of epilepsy with ASD, and the identification of ASD-predisposing mutations in genes encoding synaptic proteins (i.e., SYN1, IL1RAPL1, RIMS3, NLGN3, and NLGN4)." (PMID 24312498, 2013). "The observations that SYN1 and PRICKLE1 mutations are associated with epilepsy in humans and mice suggest they are both associated with the pathogenesis of the disease." (PMID 24312498, 2013).
epilepsy (continued). "Endogenous Prickle1 and Syn1 co-localize in neurons and physically interact via the SYN1 region mutated in ASD and epilepsy." (PMID 24312498, 2013). "Like PRICKLE1, SYN1 and CNTNAP2 were also initially identified as epilepsy genes, but later studies associated them with ASDs." (PMID 24312498, 2013). "Furthermore, children more frequently had epilepsy, macrocephaly, and developmental delay, in line with the SYN1 LoF phenotype." (PMID 36742338, 2023). "Syn1 mutant mice have severe epilepsy with generalized seizures." (PMID 36742338, 2023). "Moreover, several studies of single and multiple Syn KO mice models confirmed the relationship between the Syn1/Syn2 genes, epilepsy, and autism." (PMID 36409372, 2022). "For the time being, the E373K mutation has not been identified in the SYN1 gene of patients suffering from autism spectrum disorders or epilepsy." (PMID 36409372, 2022). "Epilepsy represents one of the paramount features of SYN1-related disorders." (PMID 36568968, 2022). "Mutations in the SYN1 gene have been demonstrated to be associated with epilepsy and autism spectrum disorders with or without epilepsy." (PMID 24251104, 2013). "Identification of more individuals without epilepsy and comparison of the detailed longitudinal developmental trajectories of individuals carrying pathogenic SYN1 variants with and without epilepsy will help to clarify the role of seizures per se on neurodevelopment." (PMID 36568968, 2022). "Epilepsy, learning disabilities, speech delay, intellectual disability (ID), and autism spectrum disorder (ASD) are the most frequent clinical manifestations associated with SYN1 variants, but an extensive comparison of the clinical features and genotype-phenotype correlations are missing." (PMID 36568968, 2022). "Conversely, none of the individuals with hot-water epilepsy displayed SYN1 variants." (PMID 34078716, 2021). "Interestingly, several loss-of-function mutations in SYN1 and SYN2 genes have been identified in patients suffering of epilepsy and/or autism spectrum disorders (ASD) and SYN2 has been identified as one of the highest risk epilepsy genes in a wide screen population." (PMID 29163811, 2017). "Our work reveals acylations of several proteins related to epilepsies (GNAO1, SYN1) and a broad spectra of neurodegenerative diseases (TAU and others)." (PMID 36293175, 2022). "DNAJC5, FRRS1L, SHANK3, SYN1, and SYN2 were epilepsy-related genes." (PMID 33584793, 2020). "Considering the role of the SYN1 protein in modulating synaptic homeostasis, neurotransmission, neuronal development, synaptogenesis, maintenance of mature synapses, and neuronal plasticity, its implication in toothbrushing epilepsy was not surprising." (PMID 34616357, 2021). "Mutations in SYN1 were mainly identified in patients affected by both epilepsy and autism, whereas, mutations in SYN2 were observed in cases of ASD without association with epilepsy." (PMID 25237665, 2014). "In our combined cohort, we did not detect enrichment of DD, ID, or ASD in individuals with epilepsy, suggesting that cognitive impairment processes are not a consequence of epileptic seizures and likely arise from parallel pathophysiological processes resulting from the SYN1 alteration." (PMID 36568968, 2022).
Cognitive impairment (27 papers, 2012 to 2026). Abnormal cognition is characterized by deficits in thinking, reasoning, or remembering. "Active AEP cleaves synapsin I and generates the synapsin I C83 fragment, which affects the recycling of synaptic vesicles and causes synaptic dysfunction and cognitive impairment, promoting the onset of AD." (PMID 35443102, 2022). "Syn1 could be a particularly interesting biomarker of cognitive impairment associated with the intake of HF diets in PBMC, as its expression in these cells has a strong negative correlation with insulin resistance-related parameters." (PMID 29566703, 2018). "Furthermore, we propose that Syn1 expression in PBMCs could serve as a readily detectable and robust early biomarker for cognitive impairment linked to the consumption of fat-rich unbalanced diets, though human validation is needed." (PMID 38203399, 2023). "In our study, the blue light exposure decreased the expression of orexin‐A, PSD‐95, and SYN‐1, leading to reduced dendritic complexity and spine density, impaired synaptic plasticity in the hippocampus, and cognitive deficits." (PMID 40820617, 2025). "In summary, the AEP‐generated synapsin I C83 fragment induces synaptic dysfunction and cognitive impairment in tau P301S mice." (PMID 35443102, 2022). "Overexpression of AEP or the AEP‐generated synapsin I C83 fragment in mice induces synaptic dysfunction and cognitive impairment." (PMID 35443102, 2022). "We further investigated the impact of the AEP‐generated synapsin I C83 fragment on synaptic dysfunction and cognitive impairment in tau P301S transgenic mice, a mouse model of tauopathy, which is related to AD and related disorders." (PMID 35443102, 2022). "We found that overexpression of full‐length synapsin I led to synaptic dysfunction and cognitive impairment in wild‐type mice, indicating that massive overexpression of synapsin I exerts detrimental effects on normal synapses in vivo." (PMID 35443102, 2022). "Traumatic brain injury (TBI): curcumin reduced oxidative damage, normalized levels of BDNF, synapsin I, and CREB and counteracted the cognitive impairment caused by TBI." (PMID 32927725, 2020). "More research is needed, either in rodents or directly in humans, to confirm the usefulness of Syn1 and to validate it as an early marker of diet-related cognitive impairment." (PMID 29566703, 2018). "It is worth mentioning that Sorl1 and Syn1 were revealed as potential early biomarkers of cognitive impairment, since their mRNA levels in PBMC remained significantly low with the intake of the HF diets throughout the dietary intervention." (PMID 29566703, 2018). "Physical exercise improves TBI-induced cognitive deficits by ample release of IL-6, synapsin I, and other nerve growth factors." (PMID 28438174, 2017). "Deletion of synapsin I induces synaptic dysfunction and cognitive impairment in mice." (PMID 35443102, 2022). "Furthermore, the expression of the synapsin I C83 fragment in tau P301S transgenic mice or wild‐type mice promotes synaptic dysfunction and cognitive impairment." (PMID 35443102, 2022). "Hence, the synapsin I C83 fragment induces synaptic dysfunction and cognitive impairment in wild‐type mice." (PMID 35443102, 2022). "Therefore, the synapsin I C83 fragment mediates synaptic dysfunction and cognitive impairment." (PMID 35443102, 2022). "Physical exercise counteracts the TBI-induced cognitive deficits by elevating the brain levels of BDNF, synapsin I, and others in the cerebral ventricles." (PMID 28438174, 2017). "This reduction, however, was prevented by TRC treatment, which suggests that synapsin I and PSD95 may be involved in the CCH-induced cognitive impairment and the protective effects of TRC treatment." (PMID 30923551, 2019).
Cognitive impairment (continued). "Studies have shown that SYN1 and SYP expression is altered in brain regions involved in learning and memory in animal models of Alzheimer’s disease (AD) and other neurodegenerative disorders, suggesting that synaptic dysfunction may contribute to cognitive impairment in these conditions." (PMID 37629211, 2023).